SLC22A5 (solute carrier family 22 member 5)
Description:
Sodium-ion dependent, high affinity carnitine transporter. Involved in the active cellular uptake of carnitine. Transports one sodium ion with one molecule of carnitine. Also transports organic cations such as tetraethylammonium (TEA) without the involvement of sodium. Relative uptake activity ratio of carnitine to TEA is 11.3. In intestinal epithelia, transports the quorum-sensing pentapeptide CSF (competence and sporulation factor) from B.subtilis which induces cytoprotective heat shock proteins contributing to intestinal homeostasis. May also contribute to regulate the transport of organic compounds in testis across the blood-testis-barrier (Probable). [Isoform 3]: Retained in the ER, unable to perform carnitine uptake.
Synonyms: OCTN2; SCD; CDSP
Tractability: Small molecule: it belongs to a druggable protein family. Antibody: UniProt places it where antibodies can reach, with high confidence; its Gene Ontology location is reachable by antibodies, with high confidence; UniProt predicts a signal peptide or a membrane-spanning region. PROTAC: ubiquitination databases record sites on it; its protein half-life has been measured.
Target class: SLC superfamily of solute carriers; Electrochemical transporter; SLC22 family of organic cation and anion transporters; Transporter
Safety:
Unwanted effects reported when the protein is acted on. In parentheses: how it was acted on, where the effect was seen, and who reports it.
periorbital edema (source: ClinPGx)
Gene: Protein-coding gene on chromosome 5 (132,369,710 to 132,395,614, forward strand). Ensembl gene ENSG00000197375.
Subcellular location: Cell membrane; Apical cell membrane; Basal cell membrane; Endoplasmic reticulum (Isoform 3)
Subcellular location (Human Protein Atlas): Mitochondria
Pathways (Reactome):
Disease: Defective SLC22A5 causes systemic primary carnitine deficiency (CDSP)
Metabolism: Carnitine shuttle
Transport of small molecules: SLC-mediated transport of organic cations
Gene Ontology:
Molecular function: (R)-carnitine transmembrane transporter activity; amino-acid betaine transmembrane transporter activity; carnitine transmembrane transporter activity; PDZ domain binding; protein binding; quaternary ammonium group transmembrane transporter activity; transmembrane transporter activity; ATP binding
Biological process: (R)-carnitine transmembrane transport; (R)-carnitine transport; carnitine transmembrane transport; carnitine transport; positive regulation of intestinal epithelial structure maintenance; quaternary ammonium group transport; response to symbiotic bacterium; response to tumor necrosis factor; response to type II interferon; sodium-dependent organic cation transport; amine transport; transport across blood-brain barrier; transmembrane transport
Cellular component: apical plasma membrane; basal plasma membrane; brush border membrane; endoplasmic reticulum; extracellular exosome; plasma membrane; cytoplasm; cytosol; membrane
Genetic constraint (gnomAD): Loss-of-function variants: 37 observed, 50.55 expected, observed/expected ratio (o/e) 0.73, 90% interval 0.56 to 0.96. The upper end of that interval is the gene's LOEUF score, 0.96, which puts it in group 4 of 6, group 1 being the genes least tolerant of losing a copy. Missense variants: 659 observed, 722.91 expected, observed/expected ratio (o/e) 0.91, 90% interval 0.85 to 0.97. Synonymous variants: 275 observed, 297.18 expected, observed/expected ratio (o/e) 0.93, 90% interval 0.84 to 1.02.
Gene-disease validity (ClinGen):
ClinGen rates the evidence that SLC22A5 causes each of these diseases.
systemic primary carnitine deficiency disease (autosomal recessive): Definitive. Systemic primary carnitine deficiency (SPCD) is a potentially lethal disorder of fatty acid oxidation characterized classically by early childhood onset cardiomyopathy often with weakness and hypotonia, failure to thrive and recurrent hypoglycemic hypoketotic seizures and/or coma.
short QT syndrome (autosomal recessive): Disputed. A genetic disease of the electrical system of the heart that consists of a constellation of signs and symptoms, consisting of a short QT interval on an EKG (< 300 ms) that does not significantly change with heart rate, tall and peaked T waves, and a structurally normal heart.
Homologues: Orthologues: chimpanzee SLC22A5 (99% identical), macaque SLC22A5 (98% identical), pig SLC22A5 (91% identical), dog SLC22A5 (90% identical), rabbit SLC22A5 (90% identical), guinea pig SLC22A5 (89% identical), mouse Slc22a5 (85% identical), rat Slc22a5 (85% identical), mouse Slc22a21 (78% identical), rat Slc22a21 (78% identical), tropical clawed frog slc22a5 (71% identical), tropical clawed frog slc22a4 (65% identical), and 46 more. Paralogues in human: SLC22A4 (76% identical), SLC22A1 (32% identical), SLC22A16 (32% identical), SLC22A13 (32% identical), SLC22A2 (32% identical), SLC22A8 (31% identical), SLC22A3 (30% identical), SLC22A7 (30% identical), SLC22A15 (29% identical), SLC22A12 (29% identical), SLC22A11 (29% identical), SLC22A6 (28% identical), and 10 more.
Diseases named in the same sentence as SLC22A5 in open-access papers:
SLC22A5 is named in the same sentence as 114 diseases in open-access papers, as found by Europe PMC text mining. Sharing a sentence is not in itself a finding about the gene and the disease. The quoted sentences say what the papers report.
carnitine deficiency (97 papers, 2010 to 2026). "Functional analysis of SLC22A5 variants can improve diagnostic accuracy in patients with primary carnitine deficiency (PCD)." (PMID 41892025, 2026). "Patient A also had a homozygous likely pathogenic variant- SLC22A5 (c.641C>T(p.Ala214val), indicative of a diagnosis of primary carnitine deficiency." (PMID 41341108, 2025). "Primary carnitine deficiency (PCD) is a rare autosomal recessive fatty acid oxidation disorder caused by variants in the SLC22A5 gene, with its prevalence and the spectrum of mutations in SLC22A5 varying across races and regions." (PMID 40069787, 2025). "The reported patient A had two homozygous variants: one pathogenic CPT II gene, confirming CPT II deficiency and a likely pathogenic variant in SLC22A5 gene indicating primary carnitine deficiency." (PMID 41341108, 2025). "Primary carnitine deficiency (PCD) is an autosomal recessive disorder of fatty acid oxidation caused by mutations in the SLC22A5 gene, which encodes the organic cation transporter 2 (OCTN2)." (PMID 40069787, 2025). "Studies have demonstrated the role of SLC22A5 in metabolic carnitine deficiency and its association with cardiomyopathy features." (PMID 38398418, 2024). "PCD is a result of defective OCTN2 caused by SLC22A5 mutations; this results in increased urine excretion of carnitine; carnitine deficiency in blood, tissues, and cells; and defective fatty acid oxidation." (PMID 37351314, 2023). "Primary carnitine deficiency (PCD) caused by pathogenic variants in the solute carrier family 22 member 5 (SLC22A5) gene is a rare autosomal recessive disease that results in defective fatty acid oxidation." (PMID 38125748, 2023). "Primary carnitine deficiency (PCD) caused by mutations in SLC22A5 lead to disturbed carnitine transport into mitochondria associated with muscular weakness and dilated cardiomyopathy (DCM)." (PMID 37802072, 2023). "Some variants in SLC22A5 cause primary systemic carnitine deficiency, skeletal myopathy, or cardiomyopathy, due to a defect in the carnitine transporter." (PMID 37498360, 2023). "The primary carnitine deficiency (PCD) is caused by defect of the organic cation transporter OCTN2 on the cell membrane, which is encoded by SLC22A5 gene and transports carnitine across the plasma membrane." (PMID 40225143, 2023). "The c.-149G>A promoter change in the SLC22A5 gene has been previously reported as the most common disease-causing variant in a cohort of patients with biochemically suspected primary carnitine deficiency." (PMID 36561316, 2022). "People with variants in the SLC22A5 gene (often referred to as carnitine transporter deficiency) which results in carnitine deficiency can have skeletal myopathy and/or cardiomyopathy." (PMID 36045366, 2022). "The primary carnitine deficiency is a rare autosomal recessive disorder of the carnitine cycle, caused by homozygous or heterozygous mutations in the SLC22A5 gene, encoding the OCTN2 carnitine transporter." (PMID 35453430, 2022). "Loss-of-function (LOF) variants in SLC22A5 (OCTN2) cause Carnitine Transporter Deficiency (CTD), a rare but potentially lethal inborn error of metabolism." (PMID 36343260, 2022). "Mutations in the SLC22A5 gene are the cause of primary systemic carnitine deficiency, and different polymorphisms in the SLC22A5 gene have been involved in susceptibility to autoimmune diseases, specifically type 1 diabetes and Crohn’s disease." (PMID 36233078, 2022). "The physiological importance of OCTN2 and of carnitine is demonstrated in mice and humans with loss of function mutations of the SLC22A5 gene, which leads to systemic carnitine deficiency due to renal losses of carnitine." (PMID 36293168, 2022). "Primary systemic carnitine deficiency in both human and rodents is caused by loss-of-function mutations in the SLC22A5/Slc22a5 gene encoding for the carnitine/organic cation transporter novel 2 (OCTN2)." (PMID 33334877, 2021).
carnitine deficiency (continued). "This syndrome is more severe than the primary carnitine deficiency caused by defects of the plasma membrane transporter OCTN2 (SLC22A5)." (PMID 33807231, 2021). "OCTN2 (SLC22A5) is the main transporter of carnitine in the bodies of both humans and mice and mutations in this gene are associated with systemic carnitine deficiency." (PMID 32183456, 2020). "Primary carnitine deficiency due to mutations in the SLC22A5 gene is a rare but well-treatable metabolic disorder that puts patients at risk for metabolic decompensations, skeletal and cardiac myopathy and sudden cardiac death." (PMID 32276632, 2020). "We show that this codon suppresses translation from the wild‐type AUG of SLC22A5, resulting in reduced OCTN2 protein levels and concomitantly lower OCTN2 transport activity explaining the carnitine deficiency in patients harboring this variant." (PMID 31187905, 2019). "Primary carnitine deficiency is an autosomal recessive disorder caused by mutations in the OCTN2‐encoding SLC22A5 gene located on chromosome 5q31." (PMID 31187905, 2019). "Primary carnitine deficiency (PCD) is an autosomal recessive disease caused by an SLC22A5 gene mutation that results in defective functional organic cation transporter 2 (OCTN2)." (PMID 30885166, 2019). "Primary carnitine deficiency (PCD) is an autosomal recessive disorder of carnitine transportation caused by mutations in the SLC22A5 that lead to low serum carnitine levels and decreased intracellular carnitine accumulation." (PMID 31364285, 2019). "Downregulation of SLC22A5 can induce primary carnitine deficiency, which is characterized by encephalopathy, cardiomyopathy, cardiomegaly, metabolic derangement, hypoglycemia, and muscle weakness." (PMID 31146342, 2019). "Systemic primary carnitine deficiency, due to carnitine transport defect, is caused by biallelic variants in SLC22A5." (PMID 31500110, 2019). "Sanger sequencing of the coding regions of the SLC22A5 gene in 236 individuals with possible primary carnitine deficiency revealed bi‐allelic mutations in 133 individuals (56.4%)." (PMID 31187905, 2019). "It suggested that SLC22A5 mutants are the predominant cause of primary carnitine deficiency in Jining." (PMID 29731766, 2018). "Of parents, 1.5% were found to harbor a P/LP variant related to a self-reported secondary condition, such as variants in SLC22A5 that underlie a primary carnitine deficiency (MIM:212140)." (PMID 28554332, 2017). "Very recently, carnitine deficiency due to mutations in the SLC22A5 gene encoding the ubiquitary membrane carnitine transporter OCTN2, have been associated to SQT, likely due to secondarily increased K+ channel activity." (PMID 27242528, 2016). "Primary systemic carnitine deficiency is caused by homozygous or compound heterozygous mutation in the SLC22A5 gene on chromosome 5q31." (PMID 26075114, 2015). "The diagnosis of primary systemic carnitine deficiency should be confirmed by identification of biallelic pathogenic variants of SLC22A5 by molecular genetic testing." (PMID 26075114, 2015). "OCTN2 (SLC22A5) is a carnitine transporter, and mutations are associated with systemic carnitine deficiency." (PMID 26536134, 2015). "Primary systemic carnitine deficiency (PCD) is caused by homozygous or compound heterozygous mutation in the SLC22A5 gene (MIM # 603377) on chromosome 5q31." (PMID 26075114, 2015). "It transports as well carnitine, but in a Na+-dependent way and mutations in SLC22A5 gene can cause systemic carnitine deficiency, classified as an inherited disease OMIM212149." (PMID 24349196, 2013). "We have investigated the gross, microscopic and molecular effects of carnitine deficiency in the neonatal gut using a mouse model with a loss-of-function mutation in the OCTN2 (SLC22A5) carnitine transporter." (PMID 23112839, 2012). "Mutations in the SLC22A5 gene encoding OCTN2 cause primary carnitine deficiency." (PMID 40958655, 2025).
carnitine deficiency (continued). "This alteration can interfere with the normal function of the SLC22A5 protein, which is responsible for transporting carnitine into cells, thus having reduced carnitine uptake, leading to the characteristic features of primary carnitine deficiency." (PMID 40700042, 2025). "The clinical features of SLC22A5 variants and carnitine deficiency can vary widely." (PMID 38166572, 2024). "Moreover, variants in SLC22A5 that cause loss of OCTN2 function have been associated with primary systematic carnitine deficiency and Crohn’s disease." (PMID 36077209, 2022). "Defects in the carnitine transporter (OCTN2), which is coded by the SLC22A5 gene, create primary carnitine deficiency, expressed as low urinary carnitine excretion and low blood and tissues carnitine level, which may be a risk factor of ASD." (PMID 33805796, 2021). "It has been noted that inhibiting SLC22A5 could lead to secondary carnitine deficiency, a disease state that could give rise to problems such as muscle weakness for affected patients." (PMID 32362913, 2020). "F23F12.3/ SLC22A5 is a sodium dependent carnitine cotransporter required for beta-oxidation of long-chain fatty acids to produce ATP and is associated with primary systemic carnitine deficiency." (PMID 31834878, 2019). "Diagnosis of primary carnitine deficiency can be confirmed by DNA testing of the SLC22A5 gene." (PMID 31500110, 2019). "Primary systemic carnitine deficiency is caused by mutations of the SLC22A5 gene." (PMID 33072985, 2019). "A correlation analysis between patient phenotype and gene variant frequency showed that c.1400C>G (p.S467C) and c.51C>G (p.F17L) may be the hotspots of SLC22A5 in Primary Carnitine Deficiency in Guangxi, China." (PMID 33072985, 2019). "Among the five primary carnitine deficiency cases, four cases carried SLC22A5 mutants." (PMID 29731766, 2018). "More than 60 mutations in the SLC22A5 gene have been found to cause primary carnitine deficiency." (PMID 26075114, 2015). "Primary carnitine deficiency (PCD, MIM 212140) is an autosomal recessive disorder caused by mutations in the SLC22A5 gene, encoding the Organic Cation Transporter Novel 2 (OCTN2) protein." (PMID 40559184, 2025). "Primary carnitine deficiency (PCD, OMIM 212140) results when mutations occur in the SLC22A5 gene encoding OCTN2." (PMID 40958655, 2025). "Among the top ten common variants, DUOX2, SLC22A5, PAH, and ACADS were associated with CH, primary carnitine deficiency, hyperphenylalaninemia, and short-chain acyl-CoA dehydrogenase deficiency, respectively." (PMID 38575986, 2024). "Primary carnitine deficiency (PCD) is a rare autosomal recessive fatty acid oxidation disorder caused by variants in SLC22A5, with its prevalence and SLC22A5 gene mutation spectrum varying across races and regions." (PMID 38961493, 2024). "In primary carnitine deficiency (PCD), a recessive gene mutation in Solute Carrier Family 22 Member 5 (SLC22A5) causes a defect in the function of organic cation/carnitine transporter 2 (OCTN2), leading to a decrease in renal reabsorption of carnitine." (PMID 38254650, 2023). "The SLC22A5 gene (also known as OCTN2) codes for the organic cation transporter novel 2 and is associated with the development of primary carnitine deficiency and cardiomyopathy." (PMID 37342443, 2023). "Genetic variants in SLC22A5, encoding the membrane carnitine transporter OCTN2, cause the rare metabolic disorder Carnitine Transporter Deficiency (CTD)." (PMID 36343260, 2022). "Primary carnitine deficiency (PCD), a of carnitine cycle disorder, represents an autosomal recessive defect that occurs on the SLC22A5 (OCTN2) gene." (PMID 30863740, 2019). "Primary carnitine deficiency (OMIM# 212140, PCD) is an autosomal recessive disorder caused by mutations in SLC22A5 (OMIM# 603377)." (PMID 31364285, 2019). "SLC22A5 stop-gain pathogenic variants are associated with carnitine deficiency or cardiomyopathy as the only clinical phenotype without metabolic abnormalities." (PMID 38166572, 2024).